RN7SL2 (RNA component of signal recognition particle 7SL2)
Synonyms: 7SL1c; 7L30.1; RNSRP2; 7L1C
Gene: Miscellaneous RNA gene on chromosome 14 (49,862,550 to 49,862,849, reverse strand). Ensembl gene ENSG00000274012.
Gene Ontology:
Biological process: SRP-dependent cotranslational protein targeting to membrane, signal sequence recognition
Cellular component: signal recognition particle, endoplasmic reticulum targeting
Homologues: Orthologues: chimpanzee Metazoa_SRP (100% identical), macaque Metazoa_SRP (99% identical). Paralogues in human: RN7SL1 (98% identical), RN7SL3 (96% identical), RN7SL769P (88% identical), RN7SL126P (88% identical), RN7SL5P (88% identical), RN7SL230P (88% identical), RN7SL444P (88% identical), RN7SL45P (88% identical), RN7SL147P (87% identical), RN7SL300P (87% identical), RN7SL220P (87% identical), RN7SL296P (87% identical), and 708 more.
Diseases named in the same sentence as RN7SL2 in open-access papers:
RN7SL2 is named in the same sentence as 6 diseases in open-access papers, as found by Europe PMC text mining. Sharing a sentence is not in itself a finding about the gene and the disease. The quoted sentences say what the papers report.
colorectal cancer (1 paper, 2025). A primary or metastatic malignant neoplasm that affects the colon or rectum. "The Rn7sk, Rpph1, Rn7sl1, Rn7sl2, Znf460, Snord17, Snora73b, H1-4, H4c12, and H3c7 genes were discovered to be highly upregulated in the tumor tissue collected from colorectal cancer patients." (PMID 40427657, 2025).
pancreatic cancer (1 paper, 2025). "RN7SL2′s effect on human health has not been broadly researched, but it is one of the most differentially expressed genes in pancreatic cancer." (PMID 41010012, 2025).
tumor (4 papers, 2023 to 2025). "Lymphocyte genes in MM samples which were very downregulated compared to those in HC samples included MYH9, RN7SL2, ACTB, AHNAK and FLNA, which play important roles in cell motility, cell structure, cell migration and tumour metastasis." (PMID 37914759, 2023). "RT‐PCR detection of budding RTP gene‐expressions in PDX model post two times 8 Gy irradiation revealed that most RTP gene levels (CST3, CDC37, IGFBP6, ISYNA1, RN7SL2) increased on day 9 when RTP cells were significantly enriched and partial fell back on day 82 when tumor repopulated." (PMID 36658726, 2023).
cancer (2 papers, 2022 to 2025). A tumor composed of atypical neoplastic, often pleomorphic cells that invade other tissues. "RN7SL2 is another small, cytoplasmic RNA molecule that is highly expressed in the cell-free plasma of cancer patients." (PMID 41303378, 2025). "Several housekeeping genes, such as ACTB, TUBB1, and PTMA, as well as noncoding RNAs, such as srpRNA (RN7SL2), are highly abundant in the plasma of both cancer patients and HDs." (PMID 35816095, 2022).
RN7SL2 also shares sentences with these, for which no sentence is quoted: COVID-19 (1 paper); Stroke (1).